WDR5B (WD repeat domain 5B)
Description:
Plays a role in the proliferation of retinal pigment epithelial (RPE) cells. May function as a substrate receptor for CUL4-DDB1 ubiquitin E3 ligase complex (By similarity).
Synonyms: FLJ11287
Tractability: PROTAC: ubiquitination databases record sites on it.
Gene: Protein-coding gene on chromosome 3 (122,411,846 to 122,416,464, reverse strand). Ensembl gene ENSG00000196981.
Subcellular location: Nucleus
Subcellular location (Human Protein Atlas): Nucleoplasm
Gene Ontology:
Cellular component: nucleoplasm; nucleus
Genetic constraint (gnomAD): Loss-of-function variants: 17 observed, 25.24 expected, observed/expected ratio (o/e) 0.67, 90% interval 0.46 to 1.01. The upper end of that interval is the gene's LOEUF score, 1.01, which puts it in group 4 of 6, group 1 being the genes least tolerant of losing a copy. Missense variants: 368 observed, 404.92 expected, observed/expected ratio (o/e) 0.91, 90% interval 0.83 to 0.99. Synonymous variants: 150 observed, 155.37 expected, observed/expected ratio (o/e) 0.97, 90% interval 0.85 to 1.11.
Homologues: Orthologues: chimpanzee WDR5B (99% identical), macaque WDR5B (97% identical), pig WDR5B (92% identical), dog WDR5B (90% identical), rabbit WDR5B (86% identical), guinea pig Wdr5b (85% identical), rat Wdr5b (85% identical), zebrafish wdr5 (85% identical), mouse Wdr5b (83% identical), Drosophila melanogaster wds (78% identical), Drosophila melanogaster CG10931 (51% identical). Paralogues in human: WDR5 (86% identical), POC1A (28% identical), POC1B (28% identical), SNRNP40 (27% identical), TEP1 (27% identical), WDR17 (26% identical), PAFAH1B1 (23% identical), AHI1 (22% identical), WDR27 (22% identical), WDR38 (22% identical), WDR7 (21% identical), MAPKBP1 (19% identical), and 14 more.
Diseases named in the same sentence as WDR5B in open-access papers:
WDR5B is named in the same sentence as 3 diseases in open-access papers, as found by Europe PMC text mining. Sharing a sentence is not in itself a finding about the gene and the disease. The quoted sentences say what the papers report.
infection (1 paper, 2024). The state of being infected such as from the introduction of a foreign agent such as serum, vaccine, antigenic substance or organism. "Protein expression of WDR5 and WDR5B was verified by Western blot, although equal multiplicity of infection (MOI) transduction of ARPE-19 cells resulted in ~5-fold higher WDR5-FLAG levels compared to WDR5B-FLAG." (PMID 39056772, 2024).
tumor (1 paper, 2024). "Interestingly, a genome-wide CRISPR-Cas9 screen found that loss of WDR5B reduced the cellular fitness of several tumor cell lines." (PMID 39056772, 2024).
WDR5B also shares sentences with these, for which no sentence is quoted: age-related macular degeneration (1 paper).